EGFR (epidermal growth factor receptor)
Diseases named in the same sentence as EGFR in open-access papers (continued):
Sharing a sentence is not in itself a finding about the gene and the disease.
gastric cancer (continued). "We verified that gastric carcinoma with alterations of EGFR (somatic mutations or copy number variation) showed a significant increase of tumour size (p = 0.0094) in comparison to wild-type EGFR carcinomas." (PMID 18199332, 2008). "Given its possible therapeutic relevance, in the present study we aimed to clarify the relevance of EGFR structural alterations in gastric carcinogenesis by analyzing a series of primary gastric carcinomas for copy number and mutations in the tyrosine kinase domain (exons 18–21) of the EGFR gene." (PMID 18199332, 2008). "Interestingly, advanced gastric cancer with strong expression of epidermal growth factor receptor (EGFR) is closely associated with high LNR, and EGFR signaling is known to affect immune response by activating regulatory T cells during human cancer development." (PMID 28857489, 2017). "In addition, several transcription factors downstream of EGFR are closely associated to poor outcome of gastric cancer patients, which might contribute to REG4 inducement after EGFR ligands stimulation." (PMID 27036049, 2016). "Thus suggested that evaluation of high methylation levels of EGFR may be useful in identifying high-risk gastric cancer patients who eligible for multimodal treatments." (PMID 25959250, 2015). "First, CCND1 amplification has been linked to resistance to the EGFR inhibitor gefitinib in experimental models of head & neck cancer, raising the possibility that it might also negatively impact the efficacy of potential anti-EGFR therapy in gastric cancer." (PMID 25649416, 2015). "Recent studies showed that gastric cancer (GC) was associated with polymorphisms of the EGFR gene and environmental influences, such as lifestyle factors." (PMID 23555641, 2013). "Despite frequent Epidermal Growth Factor Receptor (EGFR) amplification and overexpression in gastric cancer, limited therapeutic responses were observed in existing EGFR-targeted agents." (PMID 40830980, 2025). "Using EGFR-high copy number gastric cancer cell lines, primary cells and subcutaneous tumor models in nude mice, we systematically evaluated pyrotinib’s anti-tumor activity through viability assays, apoptosis analysis, and transcriptomic profiling." (PMID 40830980, 2025). "EGFR-targeted therapies, such as cetuximab, have yielded disappointing results in unselected advanced gastric cancer patients, although their potential role in strictly defined EGFR-amplified subgroups is still being explored." (PMID 40458806, 2025). "Gastric cancer cell-derived EVs can deliver EGFR to remodel the liver microenvironment and promote liver-specific metastasis." (PMID 39759123, 2025). "Pyrotinib selectively suppressed proliferation, induced apoptosis, and chemosensitized in EGFR-high copy number gastric cancer models." (PMID 40830980, 2025). "A kinome-wide CRISPR/Cas9 screen in FGFR2-amplified gastric cancer cell lines (e.g., KatoIII) demonstrated that loss of focal adhesion kinase (ILK) and suppression of EGFR/HER2 signaling increased sensitivity to FGFR inhibition." (PMID 41227318, 2025). "Although EGFR is upregulated in gastric cancer, EGFR-targeted therapies have shown marginal clinical effect in gastric cancer patients without any predictive biomarkers." (PMID 39838173, 2025). "CircSLC22A23 promotes gastric cancer cell proliferation, migration, and invasion by participating in the regulation of epidermal growth factor receptor (EGFR) transcription through the activation of HNRNPU protein expression." (PMID 40708910, 2025). "Previous studies have established that afatinib sensitivity correlates with EGFR/ERBB2 co-amplification in gastric cancer, highlighting the prospective therapeutic potential of pan-HER inhibitors in clinical practice." (PMID 40830980, 2025). "Immunohistochemistry staining showed that Ephrin A1 protein levels were positively correlated with the activation status of EGFR in gastric cancer patients." (PMID 39838173, 2025).
gastric cancer (continued). "Targeting the epidermal growth factor receptor (EGFR) also represents a primary approach in gastric cancer therapy." (PMID 40530331, 2025). "Studies have shown that overexpression of EGFR often occurs in gastric cancer and promotes chemotherapy resistance in cancer cells, which is associated with poor prognosis." (PMID 40296904, 2025). "In pursuing this concept, we analyzed for the first time the effects of a class I-selective HDACi treatment on the possible upregulation of components of the oncogenic EGF receptor (EGFR) signalling pathway (receptor or ligands) in gastric cancer cells." (PMID 39864337, 2025). "To further address the clinical relevance between Ephrin A1 expression level and EGFR phosphorylation level in gastric cancer patients, we performed a human gastric tumor tissue array analysis." (PMID 39838173, 2025). "EVs derived from stomach cancer cells encapsulate proteins such asclaudin-7, CD44v6, CD44, c-MET, EGFR, EpCAM, and GPC1, all of whichare closely associated with the progression of gastric cancer." (PMID 40720603, 2025). "Consistent with our findings, Ephrin A1 expression level was positively correlated with EGFR phosphorylation level in gastric cancer patients." (PMID 39838173, 2025). "Proteomics analyses in gastric cancer cells treated with entinostat revealed a marked upregulation of EGFR in the majority of cell lines and an even more robust induction of the EGFR ligand AREG." (PMID 39864337, 2025). "Thees data confirmed a significant relationship between EGFR expression and promoter methylation, indicating that hypermethylation stabilizes and upregulates EGFR in gastric cancer." (PMID 39858030, 2025). "Research points to the involvement of the EGFR/JNK/ERK signaling pathway in regulating chemoresistance mechanisms in gastric cancer; however, reports on its role in liver cancer resistance studies are limited." (PMID 40486881, 2025). "Previous studies have demonstrated that H. pylori infection increased EGF protein and epidermal growth factor receptor (EGFR) mRNA expression in patients with chronic active gastritis, gastric ulcers, duodenal ulcers, and gastric cancer." (PMID 39857676, 2025). "Since previous studies in other tumor entities showed a downregulation of EGFR by HDACi, our findings thus indicate essential differences in the adaptive response of gastric carcinoma cells." (PMID 39864337, 2025). "The fact that HDACi treatment exerted a predominantly (EGFR) or consistently (AREG) inducing effect in the case of gastric carcinoma cells is striking." (PMID 39864337, 2025). "Our findings establish the profound upregulation of the EGFR/AREG axis by entinostat as starting point for a rational combination therapy in gastric carcinoma." (PMID 39864337, 2025). "Combination of FGFR inhibitors with EGFR or MAPK pathway inhibitors can also be considered given that FGFR inhibitor AZD4547 has synergic activity with EGFR inhibitor cetuximab in gastric cancer cells with FGFR2 amplifications." (PMID 38255923, 2024). "Among these hub genes, EGFR exhibited the highest expression and HR, making it a prime candidate for targeted therapy against gastric cancer." (PMID 39434198, 2024). "Tumour-derived EGFR (epidermal growth factor receptor)-containing exosomes are capable of remodelling the liver microenvironment presenting a novel mechanism concerning liver-tropism of gastric cancer metastasis." (PMID 38200509, 2024). "Consistently, downregulation of CD82 by miR-197 was found to increase gastric cancer cell aggressiveness and enhance EGFR phosphorylation, ERK1/2 phosphorylation and MMP7 expression." (PMID 38389703, 2024). "The findings revealed that the positive rates of c-CBL, CBL-b, and EGFR in the gastric cancer group were significantly higher compared to the normal group (71.0% vs. 18.0%)." (PMID 39130630, 2024). "In the current study EGFR has been predicted as an important therapeutic target against gastric cancer." (PMID 39434198, 2024).
gastric cancer (continued). "Specifically, Adociaquinone A demonstrates promising potential as a bioactive drug against EGFR in gastric cancer, warranting further investigation." (PMID 39434198, 2024). "In gastric cancer, gentiopicroside inhibits the proliferation of gastric cancer by regulating the EGFR/PI3K/AKT signaling pathway." (PMID 39570876, 2024). "One notable finding is the significantly elevated expression levels of epidermal growth factor receptor (EGFR) proteins in gastric cancer tumour cells, ranging between 40% and 60%." (PMID 39434198, 2024). "For example, exosomes containing EGFR influence the liver microenvironment, facilitating the metastasis of gastric cancer to the liver." (PMID 38200509, 2024). "EGFR has been identified as a critical therapeutic target and its domain structure was specifically targeted in our drug design studies against gastric cancer." (PMID 39434198, 2024). "Autocrine and paracrine ACh-induced activation of M3R and EGFR downstream signaling stimulates human gastric cancer cell proliferation." (PMID 38791353, 2024). "In this study, the immunohistochemical method was used to measure the expression levels of c-CBL, CBL-b, and EGFR in 124 gastric cancer tissue samples and 16 normal gastric mucosa samples." (PMID 39130630, 2024). "The correlation between EGFR overexpression and poor prognosis in advanced gastric cancer suggests the utility of EGFR-targeted therapies." (PMID 39199633, 2024). "The development of gastric cancer is also influenced by errors in the epidermal growth factor receptor (EGFR) pathway, specifically in the PI3K-AKT-mTOR signalling cascade." (PMID 38595903, 2024). "40.6% of human gastric cancer samples exhibited high expression of EGFR (IHC score, 3 +) and 59.4% of human gastric cancer samples exhibited low expression of EGFR (1 + and 2 +)." (PMID 38982548, 2024). "LINC00152 carries out its intended action by attaching to the epidermal growth factor receptor (EGFR) to activate the EGFR-mediated pathway, leading to the carcinogenesis of gastric cancer." (PMID 38786611, 2024). "β-elemene inactivates the miR-1323/Cbl-b/EGFR pathway to prevent the metastasis of multidrug-resistant gastric cancer cells." (PMID 38879549, 2024). "In this study, PAICS deficiency induced DNA damage in EGFR wild‐type NSCLC cells, which is consistent with the role of PAICS in gastric cancer." (PMID 38463398, 2024). "The nervous system is involved in increasing resistance to treatment, which is performed by inhibiting apoptotic cells, as happens in cervical, breast, and gastric cancer by activating β2-ARs where anti-EGFR treatment and chemotherapy resistance occur." (PMID 39337103, 2024). "The phase I Dual ErbB Inhibition in Oesophago-gastric Cancer (DEBIOC) clinical trial assessed the efficacy of a small-molecule inhibitor with equipotent activity to EGFR, HER2 and HER3 (AZD8931) in combination with Xelox." (PMID 39395265, 2024). "According to the new studies, EGFR is considered as the main target goal of the gastric cancer therapy." (PMID 39434198, 2024). "TAX prevented further deterioration of gastric cancer by inhibiting the EGFR/AKT1 signaling pathway." (PMID 39086391, 2024). "Its interactions with EGFR and c-CBL disrupt the normal degradation of EGFR, thus contributing to the enhanced EGFR signaling in gastric cancer cells." (PMID 39130630, 2024). "This suggests its potential as a therapeutic agent against gastric cancer, leveraging EGFR as a druggable target." (PMID 39434198, 2024). "By regulating the miR-1323/CBL-b/EGFR signaling axis, β-elemene inhibits the metastasis of multi-drug resistant gastric cancer cells." (PMID 39130630, 2024). "Gastric cancer cell‐derived exosomal EGFR promotes liver‐specific metastasis in Kupffer cells and hepatic stellate cells by enhancing HGF signalling in the liver." (PMID 38661437, 2024).
gastric cancer (continued). "Specifically, miR-7 suppresses the invasion and metastasis of gastric cancer through the inhibition of the epidermal growth factor receptor (EGFR) and nuclear factor-κB (NF-κB) signaling pathway." (PMID 38397398, 2024). "Research by Zhang Ming has found that EGFR secreted by gastric cancer cells in exosomes can be transferred to the liver and integrated into the plasma membrane of hepatic stellate cells." (PMID 39703839, 2024). "In gastric cancer tissues, Gαi1 immunoprecipitated with multiple RTKs (EGFR, PDGFRα and FGFR) as well as the adapter protein Gab1, mediating downstream Akt-mTOR activation." (PMID 38049415, 2023). "It is anticipated to provide new therapeutic options for EGFR-TKI-resistance patients, addressing EGFR-TKI resistant in gastric cancer." (PMID 37305567, 2023). "EGFR is highly expressed in 40–60% of gastric cancer cells and targeting EGFR is a current therapeutic strategy for preventing the development of gastric cancer." (PMID 36674593, 2023). "Recent studies demonstrated that miR-218-5p served as a tumor suppressor to inhibit tumor growth and development by targeting endoplasmic reticulum oxidoreductase one alpha (ERO1A), COMMD8, CDK6, and EGFR in lung, liver, and gastric cancer." (PMID 36831545, 2023). "The anticancer activity of anti-EGFR VHHs was further enhanced by introduction of a CPP called iRGD in gastric cancer therapy in ex vivo and in vivo models." (PMID 37746282, 2023). "Exosomes carrying epidermal growth factor receptor (EGFR) released by GC(gastric cancer) cells promote the formation of liver-specific metastases." (PMID 37456253, 2023). "Our recent study of Noggin in gastric cancer also revealed another dark side in cancers, as it facilitated proliferation of gastric cancer cells, by an upregulation of EGFR and its downstream signalling and also promoted EMT." (PMID 37333824, 2023). "Human epidermal growth factor receptor-2 (HER-2), a member of the epidermal growth factor receptor (EGFR) family, is an important treatment target for gastric cancer." (PMID 37773114, 2023). "For example, in patients with gastric cancer, high Noggin expression is associated with a poor prognosis, and Noggin promotes the proliferation of gastric cancer cells by upregulating EGFR signaling." (PMID 38012621, 2023). "As a biologically active ingredient, it can inhibit the expression of the proto-oncogene c-Myc by affecting the MAPK/ERK pathway initiated by EGF/EGFR, thereby inhibiting the proliferation of gastric cancer cells." (PMID 36674593, 2023). "MDK was found to support progression of gastric cancer, and increased EGFR signaling under hypoxia through interaction with NCL." (PMID 37081869, 2023). "We confirmed that the silkworm carboxypeptidase inhibitor inhibited the expression of c-Myc through the MAPK/ERK pathway initiated by EGF/EGFR, thereby affecting the related cyclins and inhibiting the proliferation of gastric cancer cells." (PMID 36674593, 2023). "In gastric cancer HER-2, EGFR, Akt, HIF-1α and other proteins—all linked to HSP90—appear to be potential targets." (PMID 36966394, 2023). "It has been reported that berberine suppressed EGFR/STAT3 signaling pathways in gastric cancer cell lines." (PMID 36770659, 2023). "Numerous studies have revealed that high expression of EGFR is related to gastric cancer, and 53.7% of gastric cancer tissues express EGFR." (PMID 37285389, 2023). "As there are now several therapies available to target EGFR signaling during cancer, more work is needed to clarify the role(s) of amphiregulin in our model and in gastric cancer." (PMID 37674528, 2023). "Another study by the same authors indicated a correlation between CT texture parameters and immunohistochemical biomarkers such as E-cadherin, Ki67, VEGFR2 and EGFR in 139 patients with gastric cancer." (PMID 38136387, 2023). "TAX significantly suppresses the proliferation and tumor formation of gastric cancer cells by inhibiting EGFR/AKT1 signaling pathway." (PMID 37567936, 2023).
gastric cancer (continued). "Currently, several ADCs are under investigation in clinical trials for gastric cancer patients, targeting various receptors such as EGFR, HER-2, HER-3, CLDN18.2, Mucin 1, among others." (PMID 37305567, 2023). "Gastric epithelial EGFR inhibition represents a potential strategy to prevent the development of gastric cancer in H. pylori-infected individuals." (PMID 36299773, 2022). "In earlier work, LINC01485 has been reported to promote the growth and migration of gastric cancer cells by inhibiting EGFR ubiquitination and activating its downstream Akt signal." (PMID 35663324, 2022). "For instance, trastuzumab is used for human EGFR-2 positive gastric cancer, and pembrolizumab is used for second-line and later-line treatment of gastric cancer with highly microsatellite instability/different mismatch repair (MSI-H/dMMR)." (PMID 36148016, 2022). "In vivo experiments on a MET-resistant gastric cancer cell line revealed that EGFR signaling became the primary and independent driver for the downstream signaling pathway mitogen-activated protein kinase (MAPK)/extracellular signal-related kinase (ERK)." (PMID 36338758, 2022). "We recently reported that the anti-epidermal growth factor receptor (EGFR) -targeted drug cetuximab facilitated the formation of DISC in gastric cancer cell lipid rafts, which promoted TNF-related apoptosis-inducing ligand (TRAIL)-induced apoptosis." (PMID 35785165, 2022). "MICAL-L2 has been reported to mediate the endocytic recycling of occludin, while we have also recently shown that MICAL-L2 promotes the migration of gastric cancer cells via inhibiting EGFR transportation and degradation." (PMID 35501725, 2022). "Dysregulational EGFR, KRAS, and mTOR pathways cause metabolic reprogramming, leading to progression of gastric cancer." (PMID 36145507, 2022). "The knockout of SPG20 promotes gastric cancer cell proliferation, in vitro G2/M arrest and in vivo tumor growth through the activation of the EGFR/MAPK pathway." (PMID 35627246, 2022). "Immunohistochemical analyses demonstrated that EGFR was expressed in about 50% of gastric cancer patients." (PMID 35453596, 2022). "FRAS1 was reported to facilitate the liver metastasis of gastric cancer through activating the EGFR and PI3K signaling pathways." (PMID 36008805, 2022). "In gastric cancer, miR-143 indirectly downregulates the expression of the human epidermal growth factor receptor (HER2), which is an upstream molecule of KRAS, by silencing DEAD/H-box RNA helicase 6 (DDX6)." (PMID 36233210, 2022). "Over phosphorylation of EGFR has been observed in suspended carcinoma cells such as lung and gastric cancer cells." (PMID 35428350, 2022). "In one study, SBAs and CRCs had similar 2.5% rates of EGFR alterations, while a 4% EGFR alteration rate was seen in the gastric cancer cohort." (PMID 35267592, 2022). "DARPP-32 has been shown to promote resistance of gastric cancer cells to EGFR inhibitors by promoting an interaction between EGFR and ERBB3, which drives PI3K/AKT signaling to “bypass” EGFR TKI resistance." (PMID 34675407, 2022). "In particular, the receptors EGFR and ERBB2/3/4 and the effector KRAS are among the most mutated genes in gastric cancer." (PMID 35408991, 2022). "This supported the established communication between mAChR and EGFR, and the pivotal role of M3 in gastric cancer." (PMID 35565451, 2022). "The molecular targets of gastric cancer that have been studied in depth mainly include EGFR, HER-2, VEGF, VEGFR, mTOc-MET, HGF, etc." (PMID 36686796, 2022). "The EGFR/MAPK pathway is one of the most frequently deregulated signaling pathways in gastric cancer (The Cancer Genome Atlas Research Network, 2014)." (PMID 35993110, 2022). "To identify the LPAR(s) involved in LPA-induced EGFR transactivation in gastric cancer, we evaluated the mRNA levels of various LPARs by qRT-PCR and found that LPAR3 was more highly expressed than the others." (PMID 34658851, 2021).